PPP3CA (protein phosphatase 3 catalytic subunit alpha)
Diseases named in the same sentence as PPP3CA in open-access papers (continued):
Sharing a sentence is not in itself a finding about the gene and the disease.
osteoporosis (2 papers, 2010 to 2021). A condition of reduced bone mass, with decreased cortical thickness and a decrease in the number and size of the trabeculae of cancellous bone (but normal chemical composition), resulting in increased fracture incidence. "On the other hand, PPP3CA is also expressed in osteoclasts, playing a role in the regulation of bone resorption and its deletion results in osteoporosis." (PMID 21070662, 2010).
ovarian serous carcinoma (2 papers, 2019 to 2021). "One of the three catalytic subunits of CNA, PPP3CA, was found to be significantly associated with reduced OS in later-stage ovarian serous cancer." (PMID 34573382, 2021). "Moreover, the results of TCGA data analysis showed that higher PPP3CA expression (a catalytic subunit of the calcineurin) is associated with reduced overall survival in ovarian serous carcinoma." (PMID 31399054, 2019). "Similarly, a catalytic subunit of CN, PPP3CA, is significantly associated with reduced overall survival in ovarian serous carcinoma (p < 0.05)." (PMID 31399054, 2019).
Cerebral atrophy (1 paper, 2022). Atrophy (wasting, decrease in size of cells or tissue) affecting the cerebrum. "The phenotype of the presented SEG2_57 patient greatly overlaps with the disorders associated with PPP3CA (severe DD/ID, talipes equinovarus, cerebral atrophy, vision loss, and arthrogryposis, abnormal cranial morphology, behavioral stereotypies)." (PMID 36320065, 2022).
depression (1 paper, 2023). "Some other DE mRNAs controlled by these pathways, such as glycogen synthase kinase-3 beta (Gsk3b) and the protein phosphatase 3 catalytic subunit alpha isoform (Ppp3ca), have also been suggested to be potential contributors to the development of depression." (PMID 37505566, 2023).
Epileptic spasm (1 paper, 2025). A sudden flexion, extension, or mixed extension-flexion of predominantly proximal and truncal muscles that is usually more sustained than a myoclonic movement but not as sustained as a tonic seizure. "Combining the results from our study and the literature, the most common seizure type in patients with PPP3CA variants was epileptic spasms (30/36, 83.3%)." (PMID 40548073, 2025).
hepatitis C (1 paper, 2021). "PPP3CA was down-regulated in the chip analysis of HCC patients with hepatitis C." (PMID 33959508, 2021).
macular degeneration (1 paper, 2020). Loss of vision in the central portion of the retina (macula), secondary to retinal degeneration. "Among them, four Hyper-LGs (CKB, PPP3CA, TGFB2, and SOCS2) overlapped with risk genes in the category of “macular degeneration” in the PHGKB." (PMID 32209064, 2020).
melanoma (1 paper, 2020). A malignant, usually aggressive tumor composed of atypical, neoplastic melanocytes. "Moreover, PPP3CA was also shown to serve as one of the predictor genes in melanoma." (PMID 33718118, 2020).
memory impairment (1 paper, 2015). "PPP3CA encodes a multi-subunit phosphatase, and PPP3CA−/− mice exhibit changes in the brain consistent with hyperphosphorylation of the cytoskeletal protein substrate tau, along with memory impairment and susceptibility to immune suppression." (PMID 26161779, 2015).
pancreatic adenocarcinoma (1 paper, 2021). "In addition, the dataset from Segara and Bagea showed that the levels of PPP3CA in pancreatic adenocarcinoma were higher than those in normal tissues; their fold changes were 2.564 and 2.077, respectively." (PMID 33270085, 2021).
papillary thyroid cancer (1 paper, 2020). "However, their bioinformatics analysis based on gene chips showed that AKT3, nuclear factor of activated T-cells, cytoplasmic 2 (NFATc2), and protein phosphatase 3 catalytic A (PPP3CA) were potential targets of HSDL2 in papillary thyroid cancer." (PMID 32211805, 2020).
psoriasis (1 paper, 2019). An autoimmune condition characterized by red, well-delineated plaques with silvery scales that are usually on the extensor surfaces and scalp. "The MTORC1 gene was up-regulated in the majority of psoriasis patients in the present study, while the opposite genes, PPP3CA and PPP3CB, encoding calcineurin subunits, were down-regulated, which consequently led to reduced mRNA belonging to the MiT family." (PMID 31067781, 2019).
renal agenesis (1 paper, 2011). Renal agenesis (RA) is a form of renal tract malformation characterized by the complete absence of development of one or both kidneys (unilateral RA or bilateral RA respectively), accompanied by absent ureter(s). "It is therefore interesting to note that homozygous loss of the gene encoding the Calcineurin A-α catalytic subunit (Ppp3ca) results in a reduced nephrogenic zone and renal agenesis." (PMID 21295565, 2011).
Seizure (1 paper, 2025). A seizure is an intermittent abnormality of nervous system physiology characterized by a transient occurrence of signs and/or symptoms due to abnormal excessive or synchronous neuronal activity in the brain. "Seizure onset in most cases of PPP3CA-related DEE occurred during infancy." (PMID 40548073, 2025).
small cell lung carcinoma (1 paper, 2017). Small cell lung cancer (SCLC) is a highly aggressive malignant neoplasm, accounting for 10-15% of lung cancer cases, characterized byrapid growth, and early metastasis. "It was reported that down-regulation of PPP3CA gene expression could decrease the proliferation, the cell migration and invasion of small-cell lung cancer." (PMID 28881575, 2017).
varicocele (1 paper, 2020). A condition characterized by the dilated tortuous veins of the spermatic cord with a marked left-sided predominance. "Nonetheless, proteins, such as CLGN, FTH1, MDH1, MIF, PPP3CA, SUCLA2, and PSMA7, involved in sperm function, apoptosis, and oxidative stress were present in a low and very low abundance in the unilateral and bilateral varicocele group, respectively." (PMID 32365753, 2020).
cancer (11 papers, 2011 to 2022). A tumor composed of atypical neoplastic, often pleomorphic cells that invade other tissues. "Some genes representing the KEGG pathway “Pathways in cancer” (Pdgfra, Pdgfrb, Vegfa, PPP3ca, EphB2 and Prkcn) and the gene ontology term “regulation of transmission of nerve impulses” (Bdnf, Ngfb, Klk8 and Edn1) were also included." (PMID 22384097, 2012). "In this study, we supposed that CMTM3 may be a gene of Wnt signaling pathways and associated to some pathways in cancer progression along with CCND3, PPP3CA, and PPP3CC." (PMID 34475993, 2021). "Interestingly, in addition to PDGFRA we found four genes previously shown to be driver mutations in different cancers: SETD2, FAT4, TRIP11 and PPP3CA (highlighted genes)." (PMID 32603362, 2020). "PPP3CA was seen in the cytoplasm of carcinoma cells in 22(24.2%) of 91 CCA in TMA." (PMID 31417643, 2019). "PPP3CA was expressed in the cytoplasm of carcinoma cells in 22 cases (24.2%) of 91 CCA patients." (PMID 31417643, 2019). "PPP3CA is reported to interact with NFATs (NFATc1, NFATc2, NFATc3 and NFATc4) transcriptional factors, and have a crucial role in the regulation of immune response, and invasiveness of cancer cells." (PMID 28881575, 2017). "Because PPP3CA is reported to play an important role in invasiveness in cancers, we examined whether the C16orf74-PPP3CA interaction is required for invasion activity." (PMID 28881575, 2017). "In addition to STAT3, these included SMARCA2, a tumor suppressor involved in various cancers, SOCS1, a STAT-inhibitor, DNMT3A, with known somatic mutations in the context of clonal hematopoiesis and PPP3CA encoding calcineurin-A, involved in T-cell receptor signaling." (PMID 34874980, 2021). "We demonstrated here that the inhibition of the interaction between C16orf74 and PPP3CA using T44A and ∆PDIIIT constructs led to the suppression of the invasiveness of cancer cells." (PMID 28881575, 2017). "CAPN2, ITPR1, PPP3CA, and PRKCA were enriched in calcium-induced T lymphocyte apoptosis pathway, and not reported on tumor-host immunological interactions, but those proteins were repeatedly reported relevant to human cancers." (PMID 31258820, 2019).
tumor (9 papers, 2012 to 2025). "Tumor size (P = 0.002), vascular invasion (P = 0.001), histological grading (P = 0.011), and PPP3CA expression (P = 0.033) were statistically significant risk factors affecting the outcomes of CCA patients." (PMID 31417643, 2019). "The univariate analysis showed that tumor size (P = 0.002), vascular invasion (P = 0.001), histological grading (P = 0.011), and PPP3CA expression (P = 0.033) were statistically significant risk factors affecting the prognosis of CCA patients." (PMID 31417643, 2019). "For instance, single-cell analysis revealed that the oncogenic genes HS2ST1 and EIF3M are primarily expressed in tumor cells, while the protective gene PPP3CA is mainly expressed in immune cells." (PMID 40951342, 2025). "HS2ST1 and EIF3M were predominantly expressed in tumor cells, while PPP3CA was mainly expressed in non-tumor cells, such as immune cells." (PMID 40951342, 2025). "We observed that IDO1, IL20RB, PPP3CA, and PLAU were negatively associated with favorable outcomes and were found to participate in tumor progression, whereas ESR2 showed the opposite effect." (PMID 33718118, 2020). "HS2ST1 and EIF3M likely influence the tumor immune microenvironment by inhibiting NK cell function, whereas PPP3CA may exert protective effects by promoting the infiltration of specific immune cells." (PMID 40951342, 2025). "Of which, SMAD2, PPP3CA, MAPK1, and FOS genes are known to be involved in the regulation of tumor cell proliferation and invasion." (PMID 33959508, 2021). "Despite such discrepancies, we found two splice events from genes PPP3CA and SLC20A2 that are significantly up- and down-regulated in a tumor–specific fashion." (PMID 23181285, 2012).
neurological disorders (3 papers, 2009 to 2023). "Moreover, supporting RFX7’s potential role in neuronal development and neurological disorders, we identified regulators of neuronal processes among the novel RFX7 targets, such as JUN, SYNPO, PPP3CA, and PPP2R5D." (PMID 36864036, 2023).
PPP3CA also shares sentences with these, for which no sentence is quoted: infection (9 papers); heart failure (5); bladder cancer (2); craniosynostosis (2); Crohn disease (2); developmental and epileptic encephalopathy (2); myocardial infarction (2); neurodegenerative disease (2); neurodevelopmental disorder (2); Parkinson disease (2); prostate carcinoma (2); ulcerative colitis (2); amyotrophic lateral sclerosis (1); anorexia nervosa (1); Arrhythmia (1); arthrogryposis (1); asthma (1); atherosclerosis (1); autosomal dominant disease (1); bipolar disorder (1); Candidemia (1); colon adenocarcinoma (1); cyst (1); dementia (1); dementia with Lewy bodies (1); diabetes (1); dilated cardiomyopathy (1); Down syndrome (1); esophageal squamous cell carcinoma (1); fungal infection (1).
A further 32 diseases each share a sentence with PPP3CA in 1 paper.